TDG (thymine DNA glycosylase)
Diseases named in the same sentence as TDG in open-access papers (continued):
Sharing a sentence is not in itself a finding about the gene and the disease.
cancer (38 papers, 2010 to 2025). A tumor composed of atypical neoplastic, often pleomorphic cells that invade other tissues. "As a result, alterations in TETs and TDG have the potential to serve as drivers of cancer, even though only aberrations and mutations in TET family genes have been found in tumors." (PMID 38473997, 2024). "Several polymorphisms in TDG are associated with increased risk for cancer, although this gene has also been found to act as an oncogene, promoting tumorigenesis." (PMID 37444571, 2023). "Based on these observations, we hypothesized that TDG, similarly to MutY, may initiate aberrant excision of thymine opposite dA-AL adducts, which in turn may contribute to characteristic mutations in cancer patients exposed to AA." (PMID 40625924, 2025). "Although increased TDG expression was observed in twoadrenocortical carcinomas from patients who were positive for the p.R337H mutation, itwas not possible to infer the relationship between the p.R337H mutation andTDG levels because of the small number of cases." (PMID 25945745, 2015). "In addition, the physiological relevance of TDG and active DNA demethylation are becoming clearer since a disruption in these processes leads to symptoms of insulin resistance, loss of bile acid homeostasis, and ultimately cancer." (PMID 35159032, 2022). "This process promotes DNA damage through thymine DNA glycosylase (TDG)-driven excision, thereby unveiling a novel therapeutic strategy for cancer treatment." (PMID 40260239, 2025). "In contrast to previous reports, since decreased TDG expression induces the accumulation of 5-hydroxymethylcytosine, 5-cac and 5-fc, TDG has been suggested to serve as a protective component in malignant tumors." (PMID 39090080, 2024). "In this review, we summarize the recent findings on TDG’s function as a transcriptional regulator as well as the physiological relevance of TDG and active DNA demethylation in cancer." (PMID 35159032, 2022). "At present, the relationship between BER deficiency and cancer is limited to an autosomal-recessive MAP disease 10, and research on TDG in carcinogenesis and cancer development is limited and needs to be explored in specific cancers." (PMID 35414793, 2022). "In this review, we summarize the various functions of TDG in gene regulation as well as the physiological relevance of TDG in cancer." (PMID 35159032, 2022). "Collectively, these findings suggest that TDG possesses both tumor suppressive properties as well as oncogenic properties depending on the type of cancer involved." (PMID 35159032, 2022). "Other in vitro and in vivo studies support the involvement of TDG in cancer by showing that TDG regulates the expression of tumor suppressor genes by interacting with several transcription factors." (PMID 35628498, 2022). "In conclusion, TDG contributes significantly to enhancing the immune function, and prevents inflammation, cancer, and other diseases." (PMID 33101019, 2020). "It is conceivable that TDG is involved in aberrant DNA methylation in various cancers including lymphomas and leukemias, but conclusive data to support this is lacking." (PMID 32547565, 2020). "Meanwhile, total flavones of TDG is to down-regulate the overexpression of miRNA in cancer, and also up-regulate the expression of tumor suppressor miRNAs." (PMID 33101019, 2020). "We will further investigate the expression of TET3 and TDG in cancer and their effects on gene expression profiles in subsequent studies." (PMID 32637580, 2020).
cancer (continued). "The combined results from our in vivo mouse studies and investigation of human cancer databases indicate a role of TDG in the suppression of intestinal tumorigenesis, and particularly in sex-specific protection from CRC." (PMID 29163805, 2017). "For instance, Thymine DNA Glycosylase (TDG), which can deaminate 5hmC and therefore contribute to the reduction of the 5hmC pool, is also dysregulated in cancer cells." (PMID 26785262, 2016). "ING4, the newly identified transcription activator of TDG, is a well-defined tumor suppressor in many types of cancers." (PMID 26544625, 2015). "If this mechanism is operational with other lesions, in particular bulky lesions such as dA-AL adducts, TDG could have a role in AA-induced mutagenesis in cancer cells." (PMID 40625924, 2025). "TDG not only plays a key role in DNA repair but also participates in active DNA demethylation and gene transcription regulation, possibly serving as an instrumental contributor for cancer genesis." (PMID 39090080, 2024). "Considering its roles in DNA repair, DNA demethylation, and transcription regulation, TDG may contribute to carcinogenesis or cancer progression." (PMID 35414793, 2022). "In contrast to its tumor suppressive properties, two studies have shown that TDG can promote tumourigenesis and may be a potential target for cancer therapy." (PMID 35159032, 2022). "We also demonstrated that the expression of UHRF1, SMUG1, TDG, and MBD1/2/3 presented the most significant positive correlation with other regulators and might be the risk factors for carcinoma formation." (PMID 34552879, 2021). "The role of TDG in cancer progression is a hotly debated issue." (PMID 31239841, 2019). "On the other hand, TDG expression in human cancers can also be regulated by epigenetic changes." (PMID 26544625, 2015). "TDG was involved in DNA repair, a process frequently dysregulated in many cancers." (PMID 21114830, 2010). "Interestingly, increased TDG expression was observed in the ACC patients with the presence of the germline pR337H mutation, further suggesting a possible endocrine/hormonal relationship between TDG and cancer." (PMID 36618446, 2021). "Interestingly, depletion of TDG significantly inhibited cancer cell proliferation and tumor formation in this study, suggesting TDG is required for CRC growth and may serve as a biomarker." (PMID 25375110, 2014). "On the other hand, AMPK can inhibit DNA demethylation of the SREBP-1 promoter mediated by TDG, suggesting that TDG regulated by insulin or metformin is a potential therapeutic target for T2DM-related cancers." (PMID 35912181, 2022). "According to other authors, TDG interacts with transcription factor TCF4 and acts as a positive regulator in the Wnt pathway, is upregulated in human cancer and is required for cancer growth." (PMID 32140249, 2020). "Successes in this direction include targeted DNA methylation in cancer cells using DNMT3A coupled to zinc-finger ATFs and targeted demethylation by fusing thymine DNA glycosylase (TDG) to a sequence-specific DNA binding domain." (PMID 22771539, 2013). "Thus, TDG-mediated regulation of DNA demethylation modification holds a non-negligible relevance for cancer development." (PMID 39090080, 2024). "Although mutations or alterations in TDG have not been identified, TDG and TET genes could potentially be epigenetically silenced, contributing to cancer oncogenesis." (PMID 38473997, 2024). "This analysis also revealed a number of epigenetic oncogenes (KDM1A, HDAC1, TDG) and tumor suppressors (KAT2B, PRDM5, DUSP1, EYA4) which did not correlate significantly with any of the others, suggesting that these may affect cancer DNAm patterns independently of each other." (PMID 26169266, 2015).
tumor (33 papers, 2014 to 2024). "A heterozygous missense TDG mutation was noted in the tumor and subsequently confirmed by IHC to result in reduced TDG protein levels." (PMID 36618446, 2021). "To study the role of TDG in tumorigenesis, we analyzed the effects of its inactivation in a well-characterized model of tumor predisposition, the ApcMin mouse strain." (PMID 29163805, 2017). "In the present study, we analyzed patients’ clinicopathological characteristics and the levels of mRNAs encoding TET1–3 and TDG proteins that were present in tumor tissue." (PMID 26207381, 2015). "Loss of TET1 or TDG in CRC cells enhances the inflammatory response and improves tumor killing by NK cells." (PMID 38914477, 2024). "TDG, or Thymine DNA Glycosylase, plays a key role in active DNA demethylation and in tumor suppression." (PMID 37444571, 2023). "TDG was also found to be essential for the expression of several tumor suppressors genes in vitro, such as p15ink4b, Hic1, Rarβ, and Nr0b2." (PMID 35159032, 2022). "The recent conditional Tdg knockout studies have demonstrated TDG’s role as a tumor suppressor in vivo and as a tumor promoter in some contexts, highlighting the importance of TDG’s role for maintaining normal cellular homeostasis." (PMID 35159032, 2022). "Several conditional Tdg knockout studies performed in mice have since provided support for TDG as a tumor suppressor in vivo." (PMID 35159032, 2022). "Together, these results demonstrate that TDG inhibition can arrest tumor cell growth and eventually induce cell death." (PMID 30674989, 2019). "TDG functions as a tumor suppressor by promoting the demethylation of H3K27 in Fas promoter and activating Fas expression." (PMID 26544625, 2015). "Furthermore, TDG depletion in vivo reduces tumor growth and is a promising novel target for DNA methylation therapeutic approaches." (PMID 38914477, 2024). "The results of this study confirmed that the expression of TDG protein in Ect1/E6E7 cells was significantly higher than that in SiHa cells, suggesting that TDG protein may be a potential tumor suppressor protein or have tumor suppressive effect." (PMID 36726132, 2023). "Of note, the KRAS G12D mutant promotes proliferative signaling, cell-replicative immortality, tumor-promoting inflammation, angiogenesis, a change in cellular energetics, invasion and metastasis, and suppresses apoptosis by down-regulating the thymine-DNA glycosylase (TDG)." (PMID 36975507, 2023). "A tumor metastasis assay was performed in nude mice to determine the in vivo role of TDG." (PMID 35414793, 2022). "Recently, increasing attention has been paid to the role of TDG in tumor development." (PMID 35414793, 2022). "According to existing reports, this event that TDG has a good anti-tumor activity was confirmed." (PMID 33101019, 2020). "TET3 and TDG were significantly highly expressed in tumor tissues." (PMID 32637580, 2020). "Moreover, the extract of TDG has a certain inhibitory effect on the tumor in S180 tumor-bearing mice." (PMID 33101019, 2020). "According to multi-tumor data analysis, TET3 and TDG are highly expressed in most tumor types." (PMID 32637580, 2020). "Nowadays, many studies have shown the anti-tumor effect of TDG." (PMID 33101019, 2020). "Tumors from TDG knockdown SK28 xenografts grew significantly smaller than tumors from control SK28 xenografts, and at the end of the study, the average tumor weight of TDG knockdown xenografts was approximately half of control pLKO.1 or parental xenografts (p < 0.00006 and p < 0.0009, respectively)." (PMID 30674989, 2019). "In order to study the role of TDG in tumor formation, we generated mice bearing the conditional Tdgflox allele to bypass embryonic lethality due to germ line inactivation, and took advantage of Fabpl::Cre transgenic mice for gene inactivation in the mouse intestine." (PMID 29163805, 2017).
tumor (continued). "Considering the high expression of DNMT3A, TET1, DNMT3B, TET3, UHRF2, DNMT1, UHRF1and TDG in Subtype B, changing the tumor microenvironment cell infiltration characteristics by reversing expression of these DNA methylation regulators may be more clinically practical." (PMID 35771147, 2022). "In consideration of its role in DNA repair and demethylation, TDG may play as a tumor suppressor." (PMID 26544625, 2015). "The expression levels of three writers (DNMT1, DNMT3A, DNMT3B), two erasers (TET1, TET3), and eight readers (MBD4, ZBTB33, UHRF1, UHRF2, UNG, TDG, NTHL1, SMUG1) were dramatically higher in tumor tissues (p < 0.05)." (PMID 38317133, 2024). "In HNSCC tumor tissues, increased CpG73 methylation levels were in correlation with decreased mRNA expression of TET2 (p < 0.05) and TDG (p < 0.01)." (PMID 37367043, 2023). "Further investigation illustrated that DNMT1/3A/3B, TDG, SMUG1, UNG, NEIL1, MDB3/4, ZBTB33, and UHRF1/2 were essentially upregulated in tumor samples, while TET2, MBD1, and MBD2 were downregulated in tumor samples." (PMID 35205097, 2022). "To obtain a more comprehensive insight into the epigenetic control of tumor aggressiveness, we performed an RT-qPCR analysis of the DNA methyltransferases DNMT1, 3A, and 3B, the DNA demethylases TET1, 2, 3, and TDG, and the RNA methyltransferase TRDMT1 in relation to tumor metastasis and invasion." (PMID 37367043, 2023). "Our findings strongly suggest that TDG might inhibit metastasis in CRC and play a role similar to that of tumor suppressors." (PMID 35414793, 2022). "TDG protein is a key enzyme in the active demethylation of DNA and may be a potential tumor suppressor protein, while there is no report of TDG protein in cervical lesions." (PMID 36726132, 2023). "Thus in vitro and in vivo results indicate that, unlike tumor cells, TDG is dispensable in normal cells and tissues, which rules out significant toxicity in normal cells and tissues due to TDG inactivation." (PMID 30674989, 2019). "We reasoned that the two non-redundant (genomic and epigenomic) functions of TDG may represent a vulnerability of tumor cells that can be exploited as novel targets for treatment, because targeting TDG may have the double effect of altering DNA repair capacity and epigenetic state." (PMID 30674989, 2019).
infection (4 papers, 2019 to 2023). The state of being infected such as from the introduction of a foreign agent such as serum, vaccine, antigenic substance or organism. "At the 12-h time point post-infection, TDG expression showed significant overexpression compared to control cells, while SUMO1 remained unchanged." (PMID 37211584, 2023). "SARS-CoV-2 infection resulted in a significant overexpression of SUMO1 and TDG after 24 h but insignificant compared to control cells at 6 h post-infection." (PMID 37211584, 2023). "c-Myc, ZNF265, TDG, and VG5Q were identified to interact with Rep in PCV2-infected cells in previous studies, but the roles of these proteins in the infection and pathogenic processes of PCV2 are still unclear." (PMID 31835539, 2019). "Given the role of TDG in transcription, to gain insight into the changes in gene expression associated with TDG knockdown, we compared the transcriptomes between control and C8-infected SK28 cells 5 days after infection by RNA-seq." (PMID 30674989, 2019). "To better understand the cell cycle arrest associated with TDG knockdown, we used time-lapse videomicroscopy to track the fates of individual Mel501 cells stably expressing histone H2B-green fluorescent protein (GFP) after infection with the pLKO or C8 lentivirus." (PMID 30674989, 2019). "We also found that co-infection of SK28 cells with shRNA lentiviruses against p16 INK4A and TDG (C8) rescued the proliferation defect." (PMID 30674989, 2019). "The results showed that only the silencing of TDG could significantly decrease the production of IL-10 at 48 h post rAd-Rep2 infection, while the silencing of other Rep-binding proteins did not significantly affect IL-10 production in rAd-Rep2-infected PAMs." (PMID 31835539, 2019). "Moreover, silence of the thymine DNA glycosylase (TDG), a Rep-binding protein, significantly reduced the binding activities of NF-κB p50 and Sp1 with il10 promoter, resulting in the reduction of IL-10 production in PCV2-inoculated PAMs at the later phase of infection." (PMID 31835539, 2019).
TDG also shares sentences with these, for which no sentence is quoted: asthma (1 paper); benign tumors (1); breast tumors (1); B‐cell lymphomas (1); diabetes (1); esophageal cancer (1); familial colorectal cancer (1); gastric cancer (1); head and neck squamous cell carcinoma (1); lung adenocarcinoma (1); medulloblastoma (1); metabolic disorders (1); non-melanoma skin carcinoma (1); osteosarcoma (1); ovarian carcinoma (1); pancreatic adenocarcinoma (1); prostate carcinoma (1); rectal adenocarcinoma (1); sarcoma (1); schizophrenia (1); skin cutaneous melanoma (1).